SHBG (sex hormone binding globulin)
Diseases named in the same sentence as SHBG in open-access papers (continued):
Sharing a sentence is not in itself a finding about the gene and the disease.
metabolic syndrome (continued). "The area under the curve (AUC) and the optimal SHBG level cutoff value for identifying the presence of dyslipidemia were 0.626 and 69.0 nmol/L, respectively." (PMID 40495241, 2025). "Although this study demonstrated the potential utility of SHBG in identifying dyslipidemia, its discriminatory ability alone, as reflected by the AUC, was suboptimal." (PMID 40495241, 2025). "Future studies should focus on monitoring postmenopausal women with SHBG levels above this threshold for the development of dyslipidemia." (PMID 40495241, 2025). "This study also determined that the optimal SHBG cutoff value for the presence of dyslipidemia was 69.0 nmol/L." (PMID 40495241, 2025). "TT, LH, and SHBG levels significantly decreased with the increasing number of metabolic syndrome components (all p for trend < 0.05)." (PMID 38988998, 2024). "Currently, SHBG is considered an important biomarker for metabolic syndrome and hepatic steatosis, with potential therapeutic implications for various metabolic disorders." (PMID 38660517, 2024). "The observed effect positively correlates with a number of reports that suggested the potential use of SHBG as an inflammation in the course of metabolic syndrome." (PMID 38146533, 2023). "The changes in systemic SHBG levels have additionally been proposed as a potential biomarker for both inflammatory disorders and metabolic syndrome." (PMID 37402098, 2023). "In vitro studies showed that SHBG reduces inflammation and storage of lipid in macrophages and adipocytes, which can explain the protective effect of SHBG versus metabolic syndrome and its complications." (PMID 36421197, 2022). "Follicle-stimulating hormone and sex hormone-binding globulin were found to predict dyslipidemia in patients with PCOS." (PMID 36017313, 2022). "Older age, higher WC, higher insulin, lower FSH, and lower SHBG were predictive for dyslipidemia among Chinese women with PCOS." (PMID 34977197, 2021). "AUC of age, WC, insulin, FSH, and SHBG for dyslipidemia were 0.571, 0.683, 0.698, 0.574, and 0.698, respectively." (PMID 34977197, 2021). "The mean HOMA-IR, PPG, FINS, F-CP, ALT, AST, SUA, HDL-c, SHBG, and the rate of metabolic syndrome were significantly different among the three groups." (PMID 35145476, 2021). "Age, waist circumference, follicle-stimulating hormone, insulin and sex hormone-binding globulin were predictive for dyslipidemia among Chinese women with PCOS." (PMID 34977197, 2021). "Logistic regression found that age, waist circumference, insulin, follicle-stimulating hormone, and sex hormone-binding globulin were independent predictors for dyslipidemia." (PMID 34977197, 2021). "The current study showed that age, WC, insulin, FSH, and SHBG were predictors for dyslipidemia in women with PCOS." (PMID 34977197, 2021). "Logistic regression was used to detect the relationship between SHBG and the presence of metabolic syndrome." (PMID 33101409, 2020). "Many lines of study have postulated that a reduction in SHBG levels in patients with metabolic syndrome plays a role in the development of NAFLD, which is effectively the hepatic manifestation of metabolic syndrome." (PMID 33139661, 2020). "In logistic regression, SHBG is a protective predictor for metabolic syndrome (odds ratio = 0.96; 95% confidence interval: 0.95–0.97)." (PMID 33101409, 2020). "We also investigated relationships between omentin, leptin, sex steroids, SHBG, age, and metabolic syndrome (MS)." (PMID 32326011, 2020). "The relationship of omentin to metabolic syndrome, age, serum leptin, sex steroids, SHBG was also investigated." (PMID 32326011, 2020). "A retrospective study of 141 men reported that lower SHBG levels were related to a higher prevalence of metabolic syndrome." (PMID 33291623, 2020).
metabolic syndrome (continued). "In men, low circulating levels of total testosterone and sex hormone-binding globulin (SHBG), a determinant of testosterone bioavailability, are generally associated with abdominal and/or visceral obesity and affect metabolic syndrome." (PMID 33261185, 2020). "In this study, using adipocytes and macrophages, we focused on the in vitro effects of SHBG in inflammation as well as lipid metabolism, since lipid accumulation and inflammation are both necessary for the development of metabolic syndrome." (PMID 30046278, 2018). "Our objective was to determine the impact of metabolic syndrome and diabetic parameters on testosterone and SHBG in both MetS subjects and type 2 DM patients." (PMID 30057912, 2018). "The impact of metabolic syndrome on free and total testosterone and SHBG was investigated in this study." (PMID 30057912, 2018). "Plasma SHBG levels were negatively correlated with metabolic syndrome factors (BMI, waist circumference, and TG) and diabetic parameters (insulin and HOMA-IR)." (PMID 30057912, 2018). "Thus, a low level of SHBG may be a biomarker for the future development of metabolic risk factors (including hypertension, dyslipidemia, abdominal obesity and impaired glucose metabolism), and has been associated with a 2-fold increased risk of cardiovascular disease (CVD)." (PMID 30321217, 2018). "Numerous studies have confirmed the relationship between the serum SHBG concentration and metabolic syndrome." (PMID 30046278, 2018). "However, the underlying molecular mechanism(s) linking SHBG and metabolic syndrome remains unknown." (PMID 30046278, 2018). "Epidemiological studies have found that serum SHBG level is altered in metabolic disorders, such as abdominal obesity, dyslipidemia, and insulin resistance." (PMID 29109457, 2017). "Metabolic syndrome (MS) and non-alcoholic fatty liver disease (NAFLD) have been identified as risk factors affecting serum sex hormone binding globulin (SHBG) levels." (PMID 29109457, 2017). "SHBG levels are reduced in children born at low birth weight, in teenage children with the metabolic syndrome, and in pre-pubertal children whose parents have the metabolic syndrome." (PMID 27462374, 2016). "Two recent studies proved that FSH was a biomarker to assess the probability of metabolic syndrome better than C-reactive protein, leptin or SHBG in postmenopausal women." (PMID 25959422, 2016). "A similar picture is also shared by hypothyroidism due to associated hyperglycemia, raised levels of sex hormone binding globulin (SHBG), and dyslipidemia." (PMID 27478827, 2016). "Sex hormone binding globulin (SHBG), a glycoprotein produced by hepatocytes that transports testosterone and other steroids in plasma, is a marker for developing metabolic syndrome and T2DM." (PMID 27462374, 2016). "Non-alcoholic fatty liver disease (NAFLD), a condition of increased hepatic triglycerides in the absence of excess alcohol consumption, is associated with increased visceral adipose tissue (VAT), IR, and dyslipidemia, and with low SHBG levels." (PMID 26761949, 2016). "Conversely, the presence of low testosterone and/or SHBG predicts the development of the metabolic syndrome and T2DM." (PMID 25338765, 2014). "The prevalence of metabolic syndrome was significantly higher in the first SHBG tercile than in the second and third terciles." (PMID 24714992, 2014). "Hazard ratios for incident metabolic syndrome according to quartiles of total testosterone, SHBG and free testosterone – results from prospective studies." (PMID 25019163, 2014). "Odds ratios for prevalent metabolic syndrome according to quartiles of total testosterone, SHBG and free testosterone – results from cross-sectional studies." (PMID 25019163, 2014). "Evaluation of SHBG as a marker for metabolic syndrome among males is important because this syndrome consists of a number of factors that confer increased risk of cardiovascular diseases, which are the main group of diseases causing death in Brazil." (PMID 24714992, 2014).
metabolic syndrome (continued). "There is increasing evidence in the literature to suggest that low SHBG levels are correlated with components of metabolic syndrome." (PMID 24714992, 2014). "Odds ratios for prevalent metabolic syndrome per quartile decrease of total testosterone, SHBG and free testosterone, stratified by age and BMI – results from cross-sectional studies." (PMID 25019163, 2014). "The prevalence of metabolic syndrome was significantly higher in the first (lowest) SHBG tercile than in the second (middle) and third (highest) SHBG terciles." (PMID 24714992, 2014). "Hazard ratios for incident metabolic syndrome per quartile decrease of total testosterone, SHBG and free testosterone, stratified by age and BMI – results from prospective studies." (PMID 25019163, 2014). "The present findings indicated that SHBG levels could be the most reliable indicator of dyslipidemia among E2, TT, and DHEAS levels, as suggested by the AUC comparisons." (PMID 40495241, 2025). "Other studies have suggested an intrinsic mechanistic link between SHBG and metabolic syndrome." (PMID 40625923, 2025). "On the other hand, metabolic (non-alcoholic) fatty liver disease (MAFLD), characterized by hepatic triglyceride accumulation unrelated to excess alcohol consumption, is associated with increased visceral adipose tissue (VAT), IR, dyslipidemia and reduced SHBG levels." (PMID 40863113, 2025). "and in this study, SHBG was significantly correlated with dyslipidemia." (PMID 40495241, 2025). "This suggests that reduced SHBG levels may be a significant factor in thedevelopment of metabolic syndrome, alongside traditional factors such as hypertension, abdominal obesity, and hyperinsulinism." (PMID 39411775, 2024). "Given that dyslipidemia is an established risk factor for CHD, we aim to employ Mendelian randomization (MR) in conjunction with mediation analysis to confirm the mediating role of blood lipid levels in the association between SHBG and CHD." (PMID 38796576, 2024). "SHBG was also sowed to play an important role in activating insulin receptor activity and therefore increasing insulin sensitivity suggesting that SHBG may have a broader clinical utility in T2D or metabolic syndrome treatment." (PMID 38874666, 2024). "The increased risk of dyslipidemia and CHD associated with low SHBG levels may be largely overlooked." (PMID 38796576, 2024). "Additionally, low testosterone and sex hormone-binding globulin (SHBG) levels in men are independent predictors of metabolic syndrome." (PMID 39768643, 2024). "In addition, n-3 PUFA can improve dyslipidemia, chronic inflammatory environment, increase sex hormone binding globulin and reduce free androgen index in PCOS patients." (PMID 37111146, 2023). "Another study investigating the association between AMH and metabolic syndrome in women with PCOS concluded that AMH was positively correlated with HDL cholesterol and SHBG and negatively correlated with glucose, insulin, blood glucose, BMI, and blood pressure." (PMID 37242163, 2023). "Moreover, PCOS exhibits similar characteristics to NAFLD, such as IR, T2D, dyslipidemia, decreased sex hormone-binding globulin (SHBG), increased aminotransferase activity, and xanthine oxidase levels." (PMID 37108615, 2023). "For example, when adjusted for SHBG, the association between total testosterone with the risk of metabolic syndrome was no longer significant in males who participated in the Framingham Heart Study, suggesting a confounding effect of SHBG." (PMID 36394074, 2022). "Low total testosterone and SHBG were strongly associated with increased likelihood of having metabolic syndrome, independent of IR." (PMID 36482993, 2022). "Low testosterone and SHBG in men are independent predictors of metabolic syndrome." (PMID 36482993, 2022). "SHBG is a new sign of metabolism and inflammation and low SHBG could predict the development of metabolic syndrome." (PMID 36267567, 2022).
metabolic syndrome (continued). "Low testosterone and SHBG concentrations are related with metabolic syndrome and fatty liver." (PMID 36482993, 2022). "Moreover, the predictive role of SHBG varies among observational studies with some but not all studies reporting that low SHBG is predictive of the development of the metabolic syndrome and/ or incident T2D." (PMID 35834069, 2022). "Univariate logistic regression analysis showed that age, BMI, WC, HC, SBP, DBP, duration of infertility, glucose, insulin, and HOMA-IR were significantly associated with higher chance of dyslipidemia, while LH, FSH, and SHBG were significantly associated with lower chance of dyslipidemia." (PMID 34977197, 2021). "In our study, PCOS women with lower SHBG levels had higher mean FBS and TG levels, which is in good consistency with the hypothesis of the relationship between low SHBG with metabolic syndrome and abnormal glucose metabolism." (PMID 34458674, 2021). "Our study also found protective role of SHBG on dyslipidemia in women with PCOS." (PMID 34977197, 2021). "Age, WC, insulin, FSH, and SHBG were significant independent predictors for dyslipidemia." (PMID 34977197, 2021). "The dyslipidemia group had lower SHBG levels than the normal group." (PMID 33291623, 2020). "In addition, dyslipidemia and altered production of sex hormone-binding globulin (SHBG), leptin, and adropin appear to play a role in the pathogenesis of PCOS-associated metabolic dysfunction." (PMID 31015585, 2019). "Variants of SHBG gene were also associated with metabolic syndrome in obese women and also Mediterranean women with PCOS, suggesting that the SHBG gene may be a risk factor for PCOS." (PMID 30944702, 2019). "Whether newborn SHBG levels predict the development of overweight and metabolic syndrome remains to be determined." (PMID 27462374, 2016). "Notably, a low level of SHBG is a biomarker for the future development of the metabolic syndrome (MetS), gestational diabetes, and T2DM." (PMID 26761949, 2016). "Because insulin is a potent inhibitor of SHBG production in the liver, it is possible that decreased levels of SHBG could be an early marker for metabolic syndrome." (PMID 24714992, 2014). "In fact, the existing data in the literature are still insufficient to confirm whether SHBG is an early marker or whether it is a component of metabolic syndrome." (PMID 24714992, 2014). "Low SHBG levels seem to be a marker for the metabolic syndrome in both men and women." (PMID 23781314, 2013). "Thus, TT levels seemed to be a better indicator of metabolic syndrome status than SHBG levels in our study." (PMID 22044661, 2011). "Consequently, SHBG levels mightvary under either physiological or pathological conditions, such as pubertal andsenescence changes (increase) or in metabolic syndrome (decrease)." (PMID 40857627, 2025). "Furthermore, metabolic syndrome in men correlates with low levels of SHBG." (PMID 40427034, 2025). "Therefore, the observed relationship between SHBG and dyslipidemia might reflect sex steroid activity-independent mechanisms, suggesting the potentially direct role of SHBG in lipid metabolism." (PMID 40495241, 2025). "Moreover, low concentrations of total testosterone and SHBG were strongly associated with an increased likelihood of having metabolic syndrome, independent of other cardiovascular risk factors." (PMID 34335746, 2021). "However, other clinical trials have shown that decreased serum concentrations of SHBG, but not testosterone, are associated with the metabolic syndrome in overweight and obese women with PCOS." (PMID 33139661, 2020). "Thus, the serum SHBG concentration has been regarded as a biomarker for metabolic syndrome." (PMID 30046278, 2018). "The MASLD group showed significantly higher glycemia, dyslipidemia, and elevated liver enzymes, along with lower HDL and SHBG levels." (PMID 41295273, 2025).
metabolic syndrome (continued). "Moreover, research suggests that SHBG inhibits inflammation and lipid accumulation in macrophages and adipocytes, which may be a potential mechanism for the protective role of SHBG in reducing the incidence of metabolic syndrome and its complications." (PMID 38779450, 2024). "In the presented study, we have found that SHBG mitigates ER stress and improves cells viability and insulin sensitivity in adipose-derived mesenchymal stem cells (ASC) isolated from metabolic syndrome-affected horses (EMS)." (PMID 37697311, 2023). "Thus, SHBG may protect against the development and progression of metabolic syndrome." (PMID 33808055, 2021). "Thus, SHBG may be regarded as a good biomarker for metabolic syndrome." (PMID 30046278, 2018). "This is not unreasonable because changes in plasma SHBG levels have a pivotal role in controlling the balance between circulating androgens and estrogens, both of which are directly implicated as either risk factors or more directly in the etiology of the metabolic syndrome in men and women." (PMID 28947831, 2017). "In addition to testosterone (T), the emerging role of sex hormone-binding globulin (SHBG) in pathogenesis of metabolic syndrome (MetS) has been noted recently." (PMID 28577342, 2017). "Hepatocellular lipids were additionally related to dyslipidemia, parameters of body composition, but also to FAI and SHBG." (PMID 27505055, 2016). "At baseline, individuals with dyslipidemia exhibited significantly lower SHBG levels compared to those without dyslipidemia (P < 0.001), with median values of 65.2 nmol/L (48.3–86.4) and 80.6 nmol/L (60.4–99.1), respectively." (PMID 40495241, 2025). "PCOS women with dyslipidemia had increased age, BMI, WC, HC, SBP, DBP, duration of infertility, insulin, HOMA-IR, lower LH, FSH, LH/FSH ratio and SHBG compared to women without dyslipidemia." (PMID 34977197, 2021). "The dyslipidemia group included subjects with low high-density lipoprotein cholesterol (HDL-C), high triglycerides (TG), or a high atherogenic index of plasma (AIP); this group had lower SHBG than the normal lipid group." (PMID 33291623, 2020). "Their results also demonstrated that participants with the metabolic syndrome had statistically significant lower SHBG concentrations than those without." (PMID 30100880, 2018). "SHBG concentrations of participants with the metabolic syndrome were lower than those without [3.00 ± 0.42 vs. 3.48 ± 0.36 nmol." (PMID 30100880, 2018). "In conclusion, our study showed that SHBG is a sensitive predictor of metabolic syndrome in boys and not girls." (PMID 26962330, 2016). "In a recent non-interventional study examining 80 patients with metabolic syndrome, it was reported that an increase of one unit in insulin levels resulted in a decrease of 0.25 units in SHBG levels." (PMID 24714992, 2014). "While the mechanisms are not fully understood, current evidence suggests that the causative relationship between TD and diabetes might be bidirectional, or even multidirectional and interrelated with obesity, metabolic syndrome (MetS), sex hormone-binding globulins (SHBG), and other factors." (PMID 24069277, 2013). "Obese women with PCOS are reported to have lower serum SHBG than non-obese women with PCOS, while the SHBG concentration is inversely related to the occurrence of metabolic syndrome, which also verifies our hypothesis." (PMID 34805198, 2021). "In that study SHBG correlated positively with insulin sensitivity as estimated by HOMA-S and negatively with waist-hip ratio, BMI and DBP across all ethnic groups, whereas in multivariate logistic regression analysis a low SHBG increased the likelihood of the metabolic syndrome being present." (PMID 34386722, 2021). "Moreover, in accordance with several reports, our study also observed negative correlation of SHBG with metabolic syndrome factors (BMI, waist circumference, and TG) and diabetic parameters (insulin and HOMA-IR), which is in line with previous studies." (PMID 30057912, 2018).